MTOR (mechanistic target of rapamycin kinase)
Diseases named in the same sentence as MTOR in open-access papers (continued):
Sharing a sentence is not in itself a finding about the gene and the disease.
breast cancer (continued). "Because AMPK functions as a tumor suppressor by inhibiting the mTOR pathway, we hypothesized that the decreased PRKAG3 activity in mammary carcinoma may decrease the inhibitory effect of AMPK, leading to tumor growth." (PMID 40839607, 2025). "For the treatment of advanced ER+ breast cancer, several clinical trials have evaluated combinations of endocrine therapy and inhibitors of the PI3K/AKT/mTOR pathway, including mTOR inhibitors and dual PI3K/mTOR inhibitors." (PMID 38791941, 2024). "Consequently, it is evident that Netupitant mediates its anti-proliferative effects on breast cancer cells by targeting AGK and inhibiting the PI3K/AKT/mTOR signaling pathway." (PMID 39594764, 2024). "We identified and validated TMEM41B as a target of miR-660-5p in breast cancer cells, which aligns with previous findings that miR-660-5p promotes breast cancer progression by targeting TET2 and activating the PI3K/AKT/mTOR pathway and the miR-660-5p/TFCP2/CDKN1A pathway." (PMID 39709500, 2024). "The biological function of SAE1 may be achieved through the PI3K/Akt/mTOR signaling pathway, and SAE1 is a potential target for breast cancer treatment." (PMID 39742381, 2024). "In our earlier studies, higher doses of Vitamin D3 were used (up to 1 mM range) and revealed the downregulation of glycolysis and mTOR, as well as the alteration of EMT pathway proteins (Vimentin, E-cadherin, and N-cadherin) and lowering breast cancer cell viability." (PMID 38791386, 2024). "Importantly, a deficiency of MARCH1 promotes the migration and the colony formation of breast cancer cells, which can be blocked by H151 (STING inhibitor), GSK8612 (TBK1 inhibitor), or Torin 1 (mTOR inhibitor)." (PMID 39061024, 2024). "The combination of mTOR and AIs has been the standard of care for ER+ advanced breast cancer; however, this treatment has not demonstrated an improvement in survival in clinical trials." (PMID 39544302, 2024). "Everolimus, an mTOR inhibitor, has been studied as a treatment option for advanced HR+ breast cancer patients who have previously been treated with nonsteroidal aromatase inhibitors (AIs)." (PMID 38339303, 2024). "Research has confirmed that ISO can mediate autophagy in lung cancer cells by affecting mTOR and activate mitochondria through PI3K/PAKT/mTOR to mediate apoptosis in rectal cancer cells; in addition, it can also induce apoptosis in breast cancer cells." (PMID 39364054, 2024). "Currently, selective ER modulators (SERM), selective ER degraders (SERD), aromatase inhibitors (AIS), ovarian function inhibitors (OFS), mTOR inhibitors, and cell Cyclin-dependent kinase 4/6 (CDK4/CDK6) inhibitors are the main endocrine and targeted therapies for HR+ breast cancer patients." (PMID 38459605, 2024). "We did not include the mTOR module in this analysis, since the data for the mTOR inhibitor used in the original study, Sirolimus, were absent in PharmacoDB for most basal breast cancer cell lines." (PMID 39001416, 2024). "To determine if activation of p-mTOR occurred in breast cancer subtypes without ER, we next evaluated protein phosphorylation post exposure to FSS in the triple negative breast cancer (TNBC) cell line MDA-MB-231." (PMID 39000231, 2024). "However, metformin, known for its inhibition of the mTOR signaling pathway, was suggested to counteract the unfavorable effects of DPP-4 inhibitors on breast cancer metastasis by suppressing mTOR, indicating its potential clinical relevance." (PMID 38254789, 2024). "Furthermore, LY3484356 has displayed additivity in combination with CDK4/6 inhibitors, mTOR inhibitors, and PIK3CA inhibitors in blocking cell proliferation, as well as tumor growth inhibition in xenograft and PDX models of breast cancer." (PMID 39767607, 2024). "Curcumin inhibits breast cancer cell proliferation by altering expression of signaling proteins, including Ras, phosphatidylinositol-3-kinase (PI3K), protein kinase B (Akt), mammalian target of rapamycin (mTOR) and Wnt/β-catenin pathway." (PMID 38365810, 2024).
breast cancer (continued). "Buparlisib was heavily investigated in breast cancers with the thought that targeting both PI3K and estrogen receptors can prevent estrogen receptor (ER) activation in endocrine therapy-resistant tumors and overcome mTOR feedback activation." (PMID 38396649, 2024). "Hence, it is interest to document the molecular docking analysis of SR9009 (a pyrrolederivatives) with different breast cancer target protein targets such as HER2, Erα, PR, PI3K, AKT, Reverbα, BRMS1, Aromataseand mTOR, CDK4, CDK6, TK and Top II." (PMID 40230904, 2024). "In a previous study, it has been demonstrated that HER2 overexpression triggers activation of the HSF1-HSP90 axis and subsequently leads to the stabilization of HSP90 client proteins such as AKT, mTOR and HSF1 itself, thereby promoting tumor growth in HER2-positive breast cancer." (PMID 38646654, 2024). "In addition, it triggered programmed cell death in breast cancer cells by epigenetic alterations by upregulating Beclin 1 and LC3B while downregulating p62 and mTOR protein expression." (PMID 38563878, 2024). "Considering the existing evidence, resistance to endocrine therapy involving the PI3K/AKT/mTOR pathway in ER positive/HER2 negative breast cancer remains not completely understood." (PMID 39448637, 2024). "Further, Western blot confirmed the activation of p-mTOR in HR+ breast cancer cell lines with WT ER but not in the mutant ER cell line." (PMID 39000231, 2024). "In other studies, researchers also investigated the potential effects of ISO on breast cancer and examined the effects of ISO on the AKT/mammalian target of rapamycin (mTOR) and MAPK/MEK signaling cascades, which are two important signaling pathways for endocrine therapy resistance in breast cancer." (PMID 38650631, 2024). "The use of mTOR and PI3K inhibitors in conjunction with ET for the treatment of breast cancer may be especially problematic in patients with obesity or insulin resistance." (PMID 39251829, 2024). "In addition to mTOR, the increased phosphorylation of HER2 signaling is also in accordance with prior studies, where metastatic HR+ breast cancer had enhanced HER2 signaling." (PMID 39000231, 2024). "Everolimus, an mTOR inhibitor, was evaluated in BOLERO (Breast Cancer Trials of Oral Everolimus)." (PMID 39444377, 2024). "Based on our earlier observation that Vitamin D3 downregulates mTOR, we hypothesized that Vitamin D3 conjugated to gold nanoparticles (VD3-GNPs) reduces breast cancer aggressiveness by downregulating the key cancer controller PI3K/AKT/mTOR." (PMID 38791386, 2024). "Moreover, it also demonstrated suppressive action on the PI3K/AKT/mTOR pathway and an antioxidant effect mediated through the upregulation of the antioxidant enzymes, SOD and GPX4 against an experimentally induced mammary carcinoma animal model." (PMID 39519654, 2024). "In previous canine studies, p-mTOR is not expressed in normal mammary tissues, but in 78% of mammary carcinomas, and the expression of the mTORC2 component Rictor is positively correlated with lymphatic invasion and poorer survival." (PMID 39696035, 2024). "Moreover, PRR14 has found to be high expressed in breast cancer, and promoted cell proliferation by activating PI3K/Akt/mTOR pathway." (PMID 37325059, 2023). "We thus verified if the AKT/mTOR axis was responsible for the phosphorylation/inactivation of PTP1B by using the publicly available TCGA phosphoproteome dataset (mTOR and PTP1B phosphorylation data were only available for breast cancer, N = 42 patients)." (PMID 36697438, 2023). "Taken together, LHX2 plays a vital role in breast cancer’s progression and prognosis and could be an immune infiltration biomarker for breast cancer, and LHX2 activates the PI3K/AKT/mTOR pathway and apoptosis pathway in breast cancer." (PMID 37345110, 2023). "The current data also indicated that mTOR/HIF-1α is a dominant pathway for DPP-4 inhibition-induced autophagy in breast cancer cells, but not in normal breast epithelial cells." (PMID 37760498, 2023).
breast cancer (continued). "Likewise, in 25 breast cancer samples, miR-221 has been shown to alter the PTEN/Akt/mTOR signaling pathway, which promotes breast cancer resistance to Adriamycin." (PMID 37397377, 2023). "Multiple signaling pathways participate in the regulation of protein synthesis in breast cancer, with the well-known PI3K/AKT/mTOR pathway being a key regulator of translation initiation, promoting the synthesis of proteins essential for cell growth and survival." (PMID 37885035, 2023). "Two of the four breast cancer cell lines with SCRIB, VANGL2 and NOS1AP concomitant amplification in the CCLE collection display sensitivity to porcupine inhibitors, and one of them also shows sensitivity to drugs affecting the PI3K/AKT/mTOR pathway." (PMID 36675340, 2023). "In breast cancer, environmental stress stimulates the secretion of auto- and paracrine signaling factors, which block phosphoinositide 3-kinase (PI3K) activation and lead to the inactivation of AKT and mTOR, thereby resulting in the activation of autophagy." (PMID 37190065, 2023). "The phosphatidylinositol 3-kinase/AKT/mammalian target of rapamycin (PI3K/AKT/ mTOR) pathway is a complex intracellular metabolic pathway that leads to cell growth and tumor proliferation and plays a key role in drug resistance in breast cancer." (PMID 37646060, 2023). "Similarly, the silencing of RPS27L led to autophagy in mouse fibroblasts and human breast cancer cells via the inhibition of S6K1 phosphorylation and mTOR Complex1 activity." (PMID 36616305, 2023). "For example, in breast cancer cells, COLα1 (I) has been found to induce the intracellular PI3K-Akt-mTOR pathway including also an activation of the transcription factor YAP, nevertheless, the specific COLα1 (I) extracellular receptor inducing these pathways remains to be elucidated." (PMID 37373151, 2023). "Nevertheless, no scientometric analysis of mTOR and breast cancer has been conducted in recent years." (PMID 37637052, 2023). "NQO1 could bind to liver-type pyruvate kinase (PKLR), which activates the AMP-activated protein kinase (AMPK) and AKT/mTOR signaling pathway, and ultimately induce glycolytic reprogramming and EMT in breast cancer." (PMID 38017510, 2023). "To further elucidate SMYD3 function in the crosstalk between its binding partners AMPK and mTOR upon NCS exposure, we treated HCT-116 and AGS gastrointestinal cancer cells and the MDA-MB-231 breast cancer cell line with the novel active site-selective covalent SMYD3 inhibitor EM127." (PMID 37998381, 2023). "mTOR inhibitor and CDK4/6 inhibitor-based regimens demonstrated superior clinical efficacy and comparable safety profiles as second-line treatment in patients with HR-positive, HER2-negative advanced breast cancer." (PMID 37644396, 2023). "In our current study, PCK2 promoted mTORC1 pathway activation but did not affect the sensitivity of ER+ breast cancer cells to an mTOR inhibitor (data not shown)." (PMID 35757841, 2023). "The Breast cancer development and occurrence are relevant to multiple signalling pathways, such like the PI3K/AKT/mTOR pathway, Ras/Raf/MEK pathway, JAK/STAT pathway and cell cycle checkpoint, and it is of importance to study synergy effects of multiple pathways." (PMID 37162544, 2023). "Unfortunately, in the case of many cancers, including breast cancer, inhibitors of the MAP kinase pathway show a short-term effect due to resistance that develops from multiple bypass feedback loops, including activation of the ATK or PI3K/AKT/mTOR pathways." (PMID 37097377, 2023).
breast cancer (continued). "Inhibition of the PI3K/AKT/mTOR signaling pathway has been shown to augment the response of ER+ breast cancer to ET, indicating that dual targeting of the ER and PI3K/AKT/mTOR pathways may be another rational treatment approach." (PMID 37258523, 2023). "Breast cancer frequently experiences oncogenic activation of the phosphatidylinositol-3-kinase (PI3K), protein kinase B (PKB/AKT), and mammalian target of rapamycin (mTOR) pathway, which promotes tumor development, disease progression, and therapy resistance." (PMID 36831624, 2023). "The PI3K/AKT/mTOR pathways can be inhibited by Diras Family GTPase 3 (DIRAS3), which is found to be enriched in dormant breast cancer cells, suggesting that autophagy may contribute to tumor dormancy in breast cancer and thus plays a role in chemoresistance." (PMID 37190065, 2023). "Similarly, the overexpression of C16-Cer in breast cancer reduces the phosphorylation of ERK and Akt/mTOR, in turn reducing cell proliferation and survival." (PMID 38203299, 2023). "In addition to alterations in major cell cycle regulators, CDK4/6 inhibitor resistance in breast cancer also involves various genomic alterations, with the RAS/MAPK and PI3K/AKT/mTOR pathways playing key roles." (PMID 37511548, 2023). "Additionally, it is reported that inhibiting mTOR, which acts downstream of AKT, enhances the antitumor effects of HER2 inhibitors in HER2-overexpressing breast cancer cells." (PMID 36671478, 2023). "Aberrant regulation of other signaling pathways, including mTOR, GnRH, and TGF-bate, could result in breast cancer development." (PMID 36805828, 2023). "The use of BET protein inhibitors, already described as potential therapeutic agents in human breast cancer, is also a promising therapy in canine mammary cancer, as they can downregulate several genes related to self-renewal pathways, such as WNT, NOTCH, Hedgehog, and PI3K/AKT/mTOR." (PMID 36279498, 2022). "The treatment of the flavonoids isorhamnetin, genkwanin and acacetin against some breast cancer cell lines decreased the levels of PI3Kγ-p110, phospho-PI3K, phospho-AKT, phospho-mTOR, phospho-p70S6K, and phospho-ULK in them, thus showing their potential as an inhibitor of the PI3K/Akt/mTOR pathway." (PMID 36386899, 2022). "However, there are several treatment options available for progressive and advanced ER+ breast cancers, which include drugs that target the PI3K and mTOR signaling pathways." (PMID 36304922, 2022). "Other reports propose that MNX1-AS1 can directly or indirectly influence major signaling pathways including Jak/Stat3 and Akt/mTOR in breast cancer, MAPK in cervical cancer and also possibly Notch in LSCC." (PMID 36476366, 2022). "Such a scenario likely occurs in the case of breast cancer cells treated with NSAIDs because, in such conditions, increases in the expressions of AMPK and mTOR were observed, especially in the cases of the treatments of the cells with indomethacin, diclofenac, and sulindac." (PMID 35163433, 2022). "Hence, to confirm the magnitude of autophagy induced by the tested compound, we decided to assess the extent of mTOR inhibition in MCF-7 and MDA-MB-231 breast cancer cells after treatment with EDA-71 and cisplatin (24 h; 1.5 and 3 μM)." (PMID 36077839, 2022).
breast cancer (continued). "Altogether, our data indicate that oxidative stress, DNA damage, the Akt/mTOR and MAPK signaling pathways, and apoptosis may be involved in the synergism of cisplatin and #43 in breast cancer cells." (PMID 35662690, 2022). "Additionally, TNC can activate mTOR and NOTCH signaling pathways to promote chemotherapy resistance in breast cancer and sphere formation in brain cancer, respectively." (PMID 36289644, 2022). "In breast cancer, it is essential to note that recent research has reported Curcumin’s potential to effectively target many breast cancer-related signaling pathways, including Wnt/β-Catenin, Hedgehog, Notch, and PI3K/mTOR, as well as JAK-STAT." (PMID 36359936, 2022). "Further, the public data from the Kaplan–Meier plotter indicate that high gene expression of EGFR, mTOR, MAPK, and ERK1/2 is positively associated with shorter relapse−free survival (RFS) in ER−negative breast cancer patients." (PMID 36232636, 2022). "Further, analysis of clinical data showed a positive correlation between HDAC and mTOR in patients with triple−negative breast cancer." (PMID 36232636, 2022). "Some mTOR inhibitors have shown inhibitory function on CSC, for example, rapamycin, everolimus, and PF-04691502 can inhibit the activation of breast cancer stem cells induced by tamoxifen." (PMID 35558559, 2022). "Moreover, pairing ribociclib with PI3K/mTOR inhibitors reduced ribociclib resistance, especially in ER+/HER2− breast cancer patients, which is mediated by the PI3K/AKT pathway." (PMID 36358806, 2022). "SRC-3-AKT signaling pathway regulates autophagy of breast cancer cells to promote the proliferation of the tumor cells, and AKT further regulates mTOR signaling to form the AKT-mTOR signaling pathway that affects the poor prognosis in the patients with breast cancer." (PMID 35813295, 2022). "PI3K/Akt/mTOR activation is not ubiquitous in ER+ breast cancer and can happen at several different nodes in the pathway." (PMID 36046843, 2022). "The obtained results correlate with the degree of autophagy induction observed in the previous study, as the number of autophagosomes and autolysosomes present in breast cancer cells increased with the rise of mTOR inhibition (mTOR negative cells)." (PMID 36077839, 2022). "In our study, the increased level of this protein in G3 agreed with two complementary findings reported by two independent teams four years ago, revealing its suppression of breast cancer metastasis via the inhibition of two signaling pathways, PI3K/Akt/mTOR and YAP/TAZ." (PMID 36430209, 2022). "Downstream of PI3K/Akt is the mTOR signaling pathway, a nutrient-sensing pathway that regulate translation initiation through 4EBP1 and p70S6K phosphorylation and, along with the PI3K/Akt, is frequently dysregulated in breast cancer." (PMID 36135836, 2022). "The expression level of IQGAP3 in radiation resistant breast cancer was higher than that in radiosensitivity group, which may be related to DNA repair and PI3K-Akt-mTOR signal pathway." (PMID 36275458, 2022). "There were several hot targeting drugs in breast cancer treatment, comprising the HER-2-targeting monoclonal antibody (mAb), CDK4/6 inhibitor, poly ADP-ribose polymerase (PARP) inhibitor, PI3K/AKT/mTOR pathway inhibitor, ER targeting drugs, and aromatase inhibitor (AI)." (PMID 35402243, 2022). "Furthermore, our findings suggest that GATA3 mutations may drive resistance to hormonal therapy by upregulating the PI3K/Akt/mTOR pathway, suggesting that inhibition of MDM2 may help overcome the resistance to PI3K/Akt/mTOR inhibition and/or to endocrine therapy in GATA3-deficient breast cancer." (PMID 35440675, 2022). "In recent years, targeting agent therapy has also become one of the selective breast cancer treatment strategies, including anti-HER-2 drugs, CDK4/6 inhibitor, poly ADP-ribose polymerase inhibitor, PI3K/AKT/mTOR pathway inhibitor, ER targeting drugs, and aromatase inhibitor." (PMID 35402243, 2022).